TRPC6 (transient receptor potential cation channel subfamily C member 6)
Description:
Non-selective, calcium-permeable cation channel. Mediates calcium entry following G(q)-coupled receptor or receptor tyrosine kinase activation, which triggers phospholipase C (PLC)- mediated hydrolysis of phosphatidylinositides and production of diacylglycerol (DAG) that directly activates TRPC6. Does not appear to be activated by depletion of intracellular calcium stores. Mediates depolarization of intrinsically photosensitive retinal ganglion cells (ipRGCs) in response to light-induced melanopsin (OPN4)-mediated phototransduction via G(q)-PLC signaling, likely by forming heteromeric TRPC6-TRPC7 channels (By similarity).
Synonyms: TRP6; FSGS2
Tractability: Small molecule: a structure with a bound ligand is known; a high-quality ligand is known; it belongs to a druggable protein family. Antibody: UniProt places it where antibodies can reach, with high confidence; its Gene Ontology location is reachable by antibodies, with high confidence; UniProt predicts a signal peptide or a membrane-spanning region. PROTAC: its protein half-life has been measured; a small molecule that binds it is known.
Target class: Voltage-gated ion channel; Ion channel; Transient receptor potential channel
Gene: Protein-coding gene on chromosome 11 (101,451,470 to 101,872,562, reverse strand). Ensembl gene ENSG00000137672.
Subcellular location: Cell membrane
Pathways (Reactome):
Hemostasis: Effects of PIP2 hydrolysis; Elevation of cytosolic Ca2+ levels
Developmental Biology: Role of second messengers in netrin-1 signaling
Transport of small molecules: TRP channels
Gene Ontology:
Molecular function: calcium channel activity; inositol 1,4,5 trisphosphate binding; monoatomic cation channel activity; protein binding; protein homodimerization activity; store-operated calcium channel activity; monoatomic ion channel activity
Biological process: positive regulation of calcium ion transport; positive regulation of ion transmembrane transporter activity; calcium ion transmembrane transport; monoatomic cation transport; regulation of cytosolic calcium ion concentration; single fertilization
Cellular component: cytoplasm; membrane; plasma membrane; cation channel complex; slit diaphragm
Genetic constraint (gnomAD): Loss-of-function variants: 48 observed, 86.24 expected, observed/expected ratio (o/e) 0.56, 90% interval 0.44 to 0.71. The upper end of that interval is the gene's LOEUF score, 0.71, which puts it in group 2 of 6, group 1 being the genes least tolerant of losing a copy. Missense variants: 953 observed, 1,129 expected, observed/expected ratio (o/e) 0.84, 90% interval 0.8 to 0.89. Synonymous variants: 386 observed, 388.7 expected, observed/expected ratio (o/e) 0.99, 90% interval 0.91 to 1.08.
Homologues: Orthologues: chimpanzee TRPC6 (99% identical), macaque TRPC6 (99% identical), pig TRPC6 (97% identical), rabbit TRPC6 (97% identical), guinea pig TRPC6 (95% identical), rat Trpc6 (94% identical), mouse Trpc6 (94% identical), dog TRPC6 (82% identical), tropical clawed frog trpc6 (82% identical), zebrafish trpc6a (69% identical), zebrafish trpc6b (69% identical), Caenorhabditis elegans trp-1 (34% identical). Paralogues in human: TRPC7 (69% identical), TRPC3 (69% identical), TRPC4 (35% identical), TRPC5 (34% identical), TRPC1 (30% identical).
Diseases named in the same sentence as TRPC6 in open-access papers:
TRPC6 is named in the same sentence as 208 diseases in open-access papers, as found by Europe PMC text mining. Sharing a sentence is not in itself a finding about the gene and the disease. The quoted sentences say what the papers report.
focal segmental glomerulosclerosis (64 papers, 2009 to 2025). A renal disorder characterized by sclerotic lesions in the glomeruli. "To date, more than 30 TRPC6 variants have been reported to focal segmental glomerulosclerosis (FSGS), which can present from infancy to adulthood and is characterized by proteinuria and often nephrotic syndrome leading to kidney failure." (PMID 40409549, 2025). "Previous studies have reported persistent activation of TLRs and NLRP3 in diabetic kidney disease (DKD), IgAN, and lupus nephritis, while abnormalities or mutations in TRPC6 calcium channels are common in focal segmental glomerulosclerosis and DKD." (PMID 41476974, 2025). "Mutations in the TRPC6 gene result in podocyte damage and are associated with focal segmental glomerulosclerosis (FSGS), a chronic kidney disease leading to end-stage renal failure." (PMID 41118703, 2025). "The TRPC6 channel’s gain-of-function mutations have been discovered as a possible hereditary cause of renal disorders such as focal segmental glomerulosclerosis." (PMID 37895105, 2023). "Both TRPC6 gain-of-function and loss-of-function cause familial forms of focal segmental glomerulosclerosis (FSGS)." (PMID 35743312, 2022). "Mutations in TRPC6 lead to familial forms of focal segmental glomerulosclerosis (FSGS) and to end stage kidney disease." (PMID 35194063, 2022). "A growing interest in the potential role of TRPC6 channels in kidney injury emerged after the discovery that gain-of-function mutations in TRPC6 cause focal segmental glomerulosclerosis." (PMID 34866402, 2022). "Canonical transient receptor potential-6 (TRPC6) channels have been implicated in familial and acquired forms of focal and segmental glomerulosclerosis (FSGS), and in renal fibrosis following ureteral obstruction in mice." (PMID 35805070, 2022). "Increased expression and activity of the Ca2+ channel transient receptor potential channel 6 (TRPC6) is associated with focal segmental glomerulosclerosis, but therapeutic strategies to target TRPC6 are currently lacking." (PMID 34830371, 2021). "First, gain-of-function mutations of TRPC6 were associated with the onset of familial forms of focal segmental glomerulosclerosis; furthermore, overexpression or overactivity of wild-type TRPC6 was sufficient to cause other kidney diseases." (PMID 34095318, 2021). "Canonical transient receptor potential 6 (TRPC6) channels have been implicated in familial and acquired forms of focal and segmental glomerulosclerosis (FSGS) in patients and animal models, as well as in renal fibrosis following ureteral obstruction in mice." (PMID 33918778, 2021). "Familial focal segmental glomerulosclerosis is the most well-investigated human disease associated with multiple mutations in the TRPC6 gene." (PMID 32872338, 2020). "Gain-of-function mutations of TRPC6 lead to focal and segmental glomerulosclerosis (FSGS), a common and increasing cause of the end-stage renal disease." (PMID 32719603, 2020). "Gain-of-function (GOF) mutations of human TRPC6 (R895C) that lead to focal segmental glomerulosclerosis (FSGS) were found to be cytotoxic in different cultured cells, including podocytes." (PMID 31936014, 2020). "Mutations in canonical transient receptor potential-6 (TRPC6) channels give rise to rare familial forms of focal and segmental glomerulosclerosis (FSGS)." (PMID 29785489, 2018). "The gain-of-function mutants of TRPC6 are strongly associated with the progression of focal segmental glomerulosclerosis (FSGS)." (PMID 24709960, 2014). "Recent finding that mutations in TRPC6 gene are associated with a human proteinuric kidney disease, focal segmental glomerulosclerosis (FSGS) also links calcium signaling to podocyte injury." (PMID 21776384, 2011). "Mutations in the TRPC6 calcium channel (Transient receptor potential channel 6) gene have been associated with familiar forms of Focal and Segmental Glomerulosclerosis (FSGS) affecting children and adults." (PMID 20877463, 2010).
focal segmental glomerulosclerosis (continued). "Ever since evidence suggested that mutations in the TRPC6 gene could lead to focal and segmental glomerulosclerosis (FSGS), the research in renal TRPC channels has dramatically increased." (PMID 36613622, 2022). "However, the overexpression of TRPC6 is linked to acquired glomerular diseases, and causative gain-of-function mutations in TRPC6 cause hereditary forms of focal segmental glomerulosclerosis (FSGS)." (PMID 34830371, 2021). "In fact, gain-of-function mutations in TRPC6 can cause focal segmental glomerulosclerosis (FSGS)." (PMID 33808324, 2021). "Indeed, gain-of-function mutations of TRPC6 have been demonstrated to underlie the Focal Segmental Glomerulosclerosis (FSGS) in humans." (PMID 32787494, 2020). "Furthermore, mutations in the TRPC6 gene are associated with hereditary diseases, such as focal segmental glomerulosclerosis." (PMID 32872338, 2020). "TRPC6 (P112Q) mutant is associated with focal segmental glomerulosclerosis." (PMID 31784544, 2019). "Adult-onset familial forms of focal and segmental glomerulosclerosis (FSGS) occur with an autosomal dominant mode of inheritance in patients with mutations in the gene encoding canonical transient receptor potential-6 (TRPC6) channels." (PMID 27630573, 2016). "For example, patient mutations in the gene coding for TRPC6 are linked to familial forms of focal segmental glomerulosclerosis (FSGS), a severe kidney disorder characterized by proteinuria and progressive renal failure." (PMID 41373637, 2025). "Gain-of-function mutations in TRPC6 lead to familial forms of glomerular disease known as focal segmental glomerulosclerosis (FSGS)." (PMID 38003608, 2023). "Transient receptor potential cation channel-6 (TRPC6) gene mutations cause familial focal segmental glomerulosclerosis (FSGS), which is inherited as an autosomal dominant disease." (PMID 37615749, 2023). "Mutations in TRPC6 cause hereditary focal segmental glomerulosclerosis (FSGS), enhancing podocyte expression of wild-type." (PMID 35448080, 2022). "In humans, TRPC6 mutations are a cause of autosomal dominant focal segmental glomerulosclerosis (FSGS); the majority of these act as gain-of-function." (PMID 35749414, 2022). "TRPC6 has been implicated in the pathogenesis of kidney diseases, including focal segmental glomerulosclerosis (FSGS), diabetic nephropathy (DN), immune-mediated kidney disease, and renal fibrosis." (PMID 34483931, 2021). "In 2005, the gene mutation of TRPC6 in podocyte was firstly reported in the patients with focal segmental glomerulosclerosis (FSGS), suggesting the potential importance of TRPC6-mediated Ca2+ dynamics for podocyte function." (PMID 31998809, 2020). "Gain-of-function mutations in TRPC6 have been discovered, which mediate inherited glomerular disease such as focal segmental glomerulosclerosis (FSGS)." (PMID 27445840, 2016). "Mutations in TRPC6 are a cause of familial, autosomal-dominant, adult-onset focal segmental glomerulosclerosis (FSGS), a form of proteinuric renal disease, and increased TRPC6 expression has been observed in acquired proteinuric kidney disease." (PMID 23171048, 2012). "The canonical transient receptor potential 6 (TRPC6) has been implicated in several pathological processes, including focal segmental glomerulosclerosis (FSGS), cardiac hypertrophy, and pulmonary hypertension." (PMID 23171048, 2012). "Until today, seven different mutations in TRPC6 have been identified as a cause of autosomal-dominant focal segmental glomerulosclerosis (FSGS) in adults." (PMID 19936226, 2009). "Certain mutations in the TRPC6 gene, which most frequently result in a gain of channel function, cause podocyte diseases, including a subset of the cases of familial focal segmental glomerulosclerosis (FSGS)." (PMID 36429053, 2022).
focal segmental glomerulosclerosis (continued). "Several independent laboratories have identified TRPC6 mutations associated with the autosomal dominant form of focal segmental glomerulosclerosis (FSGS) and the critical importance of TRPC6 in the maintenance of glomerular filtration." (PMID 33922367, 2021). "Animal studies have showed that podocyte-specific transgenic TRPC6 overexpression can lead to albuminuria and histological findings similar to human focal segmental glomerulosclerosis (FSGS)." (PMID 32975098, 2020). "The functional significance of TRPC6 channels in pathogenesis of renal diseases, including focal segmental glomerulosclerosis (FSGS), diabetic nephropathy, immune-related nephropathy and chronic kidney disease was extensively studied [more details see the review]." (PMID 36277193, 2022). "Notably, upregulation of TRPC6 in myocytes plays a role in cardiac hypertrophy, and gain-of-function mutations of TRPC6 contribute to hereditary focal segmental glomerulosclerosis (FSGS), a renal disorder characterized by podocyte injury and a potential cause of end stage renal disease." (PMID 32149605, 2020). "Since this discovery, TRPC6 has been implicated in the pathophysiology of non-genetic forms of kidney disease including focal segmental glomerulosclerosis (FSGS), diabetic nephropathy, immune-mediated kidney diseases, and renal fibrosis." (PMID 31877991, 2019). "High expression of TRPC6 is detected in kidney diseases with proteinuria as the main clinical manifestation (such as glomerular minimal change disease, membranous nephropathy, and focal segmental glomerulosclerosis), as well as in some secondary glomerular diseases (such as diabetic nephropathy)." (PMID 36297636, 2022). "There are various studies suggesting that mutant TRPC6 is closely correlated with the mechanism of hereditary and non-hereditary nephropathies, such as focal and segmental glomerulo sclerosis (FSGS), minimal-change disease (MCD) and membranous glomerulonephritis (MN)." (PMID 22701654, 2012). "Non-genetic forms of such diseases like focal segmental glomerulosclerosis (FSGS), diabetic nephropathy, immune-mediated kidney diseases and renal fibrosis are attributed to TRPC6 dysregulation." (PMID 33805686, 2021).
glomerular diseases (39 papers, 2009 to 2025). "Increased TRPC6 expression and activity, either acquired or due to genetic mutations, have been shown to play key roles in the pathogenesis of glomerular diseases." (PMID 38003608, 2023). "The canonical transient receptor potential channel 6 (TRPC6) is implicated in the pathogenesis of several forms of glomerular diseases." (PMID 36672207, 2023). "TRPC6 is one of the key proteins responsible for calcium flux in the podocytes, and activation of the TRPC6 pathway is linked to multiple podocyte and glomerular diseases." (PMID 35740870, 2022). "GPCRs coupled to Gq signaling activate TRPC6, suggesting that Gq-dependent TRPC6 activation underlies glomerular diseases." (PMID 33046522, 2020). "Examining the clinical characteristics of patients with these mutations has provided insights into the role of TRPC6 in glomerular diseases." (PMID 31877991, 2019). "We have previously reported the generation of three independent transgenic mouse lines carrying different Trpc6 mutations that display a glomerular disease comparable to the phenotype presented by individuals with FSGS." (PMID 34012910, 2015). "TRPC6 is also up-regulated in primary glomerular diseases and over-expression of TRPC6 in podocytes causes proteinuric kidney disease." (PMID 25429282, 2014). "It was also shown that TRPC6 gene variation in glomerular human glomerular diseases, including MCD, FSGS, and immune complex associated glomerulonephritis, and TRPC6 overexpression in podocytes correlate with decreased calpastatin expression, autophagy blockade, and podocyte injury in DN." (PMID 41450741, 2025). "TRPC6 mutations, although more rare with regard to the number of affected families, anticipate crucial novel clues toward the understanding of hereditary forms of proteinuric glomerular diseases." (PMID 37615749, 2023). "The overexpression of TRPC6 may cause glomerular diseases such as focal segmental glomerular sclerosis (FSGS) and minimal change disease (MCD)." (PMID 34512318, 2021). "Interestingly, mice transiently overexpressing Trpc6 showed an important increase of proteinuria, which is an early sign of glomerular disease associated with podocyte injury." (PMID 34012910, 2015). "This work highlights an interesting hypothesis to explain why TRPC6 mutations only seem to induce glomerular disease, despite physiological involvement in many different cellular systems." (PMID 20674014, 2010). "In addition, TRPC6, nephrin, and podocin constitute the podocyte SD complex, which maintains the normal function of the glomerulus, and its dysregulation causes proteinuria and glomerular diseases." (PMID 34819020, 2021). "While activation of TRPC6 is essential in physiological conditions, an excessive increase in either TRPC6 expression or its channel activity may lead to pathological consequences via loss of podocytes in various forms of glomerular diseases, including DKD." (PMID 33321755, 2020). "Moreover, the phenotype variable penetrance is a well established finding in humans with FSGS related to TRPC6 mutations, suggesting that it may contribute to glomerular diseases in a multi-hit setting." (PMID 20877463, 2010). "Meanwhile, in vitro and in vivo models of glomerular diseases have also shown induced levels of TRPC6 protein in podocytes." (PMID 37615749, 2023). "For this reason, extensive drug development efforts have focused on TRPC6 as a therapeutic target for glomerular diseases and also for renal fibrosis." (PMID 36429053, 2022). "Our data suggest a pathophysiologic mechanism involving increased TRPC6 activity in response to the altered lipid content and substantiate the significance of research directed to the lipid metabolism in glomerular disease to open novel therapeutic avenues." (PMID 36429053, 2022).